CD47 (CD47 molecule)
Diseases named in the same sentence as CD47 in open-access papers (continued):
Sharing a sentence is not in itself a finding about the gene and the disease.
liver cancer (25 papers, 2015 to 2025). An epithelial or non-epithelial malignant neoplasm that arises from the liver. "To confirm the regulation of PD‐L1 and CD47 by YBX1 in human liver cancer cells, we knocked down YBX1 in HepG2 cells and LM3 cells, respectively." (PMID 38981064, 2024). "Overall, the nanosystem in this work achieved the sequential release of CDC7 and CD47 inhibitors in situ to trigger senescence and induce immunotherapy, effectively combating liver cancer and overcoming chemoresistance." (PMID 38520730, 2024). "The sequential release of a senescence inducer (CDC7 inhibitor) and a CD47 inhibitor from the dual‐targeting nanosystem in situ induced senescence and antitumor immune responses to aganist liver cancer and overcome chemoresistance." (PMID 38520730, 2024). "An additional analysis of five pairs of liver cancer specimens (GSE146049) confirmed that CD47 and CDC7 were highly expressed in HCC tissues." (PMID 38520730, 2024). "As a critical process that evolves in the TME, hypoxia affects epithelial-mesenchymal transition and angiogenesis and mainly changes the expression of immune checkpoint molecules, such as PD-L1, CD47, PD-1, and HLA-G, in liver cancer." (PMID 33596985, 2021). "For example, after the peptide ligand (TAMRA DN1K) linked with the fluorophore group was connected to MoS2 nanosheets, the nanosheets can recognize the liver cancer cells or liver cancer tissues with high expression of CD47." (PMID 32318550, 2020). "Macrophage-mediated phagocytosis of liver cancer cells can be enhanced by treatment with an anti-CD47 antibody, a SIRPα blocking antibody, or by blocking the CD47-TSP-1 interaction." (PMID 32082311, 2020). "CD47 positive liver cancer cells preferentially secreted cathepsin S (CTSS), which regulated liver tumor-initiating cells through the CTSS/protease-activated receptor 2 (PAR2) loop." (PMID 25907256, 2015). "CD47 blockade has emerged as a promising immunotherapy against liver cancer." (PMID 38520730, 2024). "HMMRhigh liver cancer cells escaped from phagocytosis via sustaining CD47 signaling." (PMID 38838151, 2024). "The down‐regulation of TUG1 in HCC cells can inhibit both PD‐L1 and CD47, which indicates that TUG1 is a potential biomarker and immunotherapeutic target for liver cancer, thereby providing new ideas for enhancing antitumor immunity." (PMID 38981064, 2024). "By screening 149 pairs of liver cancer specimens in the GEO database GSE76297, we found that CD47 and CDC7 were highly expressed in cancer tissues." (PMID 38520730, 2024). "The expression of liver cancer stem cell markers (ICAM1, CD47, CD24 and EPCAM) in HCC cells were determined by qPCR." (PMID 38169544, 2024). "A number of surface markers for liver cancer stem cell (LCSC) subpopulations (EpCAM, CD133, CD44, CD13, CD90, OV-6, CD47, and side populations) in HCC have been identified." (PMID 32466488, 2020). "Here, patients with liver cancer co‐expressing CD47 and CDC7 (cell division cycle 7, a negative senescence‐related gene) are found to have the worst prognosis." (PMID 38520730, 2024). "To further confirm the mechanism of TUG1 in regulating antitumor immunity, we downregulated TUG1 in human liver cancer HepG2 cells and found that both miR‐340 and miR‐141 were upregulated in TUG1‐downregulated cells, while the expressions of PD‐L1 and CD47 decreased." (PMID 38981064, 2024). "In addition, we downregulated TUG1 in another human liver cancer LM3 cells and found that both miR‐340 and miR‐141 were upregulated in TUG1‐downregulated cells, while the expressions of PD‐L1 and CD47 decreased." (PMID 38981064, 2024).
liver cancer (continued). "CD47 levels were found to be higher in LUAD tissues following treatment with sorafenib compared to tumor tissues prior to treatment, consistent with a report that CD47 was upregulated in liver cancers resistant to sorafenib." (PMID 37958404, 2023). "To investigate the clinical relevance of CAV1, CD47 and FLNC we analysed the transcriptomic data from 67 HCC cases in the Biostorm cohort of the Storm trial, a phase 3 clinical study exploring sorafenib as an adjuvant therapy in liver cancer patients who had previously had local ablation surgery." (PMID 40715090, 2025). "Furthermore, synergistic activities of anti-CD47 therapies and chemotherapeutic drugs can enhance the efficacy of chemotherapy in patient-derived HCC xenograft mouse models and inhibit the growth and metastasis of liver cancer cells in vivo." (PMID 32082311, 2020). "Moreover, CD47 is highly expressed, and senescence is inhibited after the development of chemoresistance, suggesting that combination therapy targeting CD47 and CDC7 to inhibit CD47 and induce senescence may be a promising strategy for liver cancer." (PMID 38520730, 2024).
B-cell lymphoma (23 papers, 2018 to 2025). "Our findings reveal, for the first time, that RTX-IgG2-mediated apoptosis is associated with a reduced and altered CD47 expression on CD20+ B-cell lymphoma cells, enhancing FcR-mediated phagocytosis by tumor-specific mAbs." (PMID 39712032, 2024). "Overexpression of CD47 has been shown to be associated with adverse prognosis in mantle cell lymphoma patients and play an important role in the dissemination of B-cell NHL." (PMID 39712032, 2024). "Collectively, our results highlight the role of RTX-IgG2 as an exclusive and target-specific enhancer for FcR-mediated phagocytosis of CD20+ B-cell lymphoma cells, an effect associated with induction of apoptosis and reduction of CD47 on target cells." (PMID 39712032, 2024). "Although the value of associating CD20 mAb therapy to CD47 modulating agents has been well established in aggressive B-cell lymphoma, both preclinically and clinically, two questions remained unanswered." (PMID 37153563, 2023). "The bromodomain extra-terminal inhibitor JQ1 suppressed the elevated CD47 expression in double-hit B cell lymphoma cells." (PMID 39201643, 2024). "The level of “don’t-eat-me” anti-phagocytic CD47 protein varies on the surfaces of different B-cell lymphoma cell lines." (PMID 39712032, 2024). "B-cell lymphoma cell lines express high levels of CD47, and DLBCL patients with high CD47 expression have poor clinical prognoses." (PMID 39060763, 2024). "This dual anti-CD20/anti-CD47 approach has provided convincing clinical results and is still being extensively evaluated, both pre-clinically and clinically, in B-cell lymphoma." (PMID 37153563, 2023). "Anti-hCD47 antibodies have also been investigated in clinical trials across various types of tumors including B cell lymphomas as therapeutics targeting the CD47-SIRPα axis." (PMID 38162643, 2023). "Here, we investigated this axis in B-cell lymphoma by assessing CD24 expression and evaluating pro-phagocytic effects of CD24 antibody treatment in comparison to hallmark immune checkpoint CD47." (PMID 35625912, 2022). "For B-cell lymphoma, a combination of CD47 antagonistic antibody with the standard-of-care CD20 antibody rituximab (RTX) yielded complete responses in relapsed and refractory patients." (PMID 35625912, 2022). "CD47 is a molecular marker expressing “self-recognition” on the cell surface, which is significantly overexpressed in various kinds of B-cell lymphoma." (PMID 34120620, 2021). "In this respect, combination of rituximab with CD47 antibody targeting is being clinically evaluated for patients with relapsed/refractory B-cell non-Hodgkin’s lymphoma (NCT02953509)." (PMID 30710089, 2019). "Using these reagents and a syngeneic mouse model of B cell lymphoma, we show that the affinity of the anti-mouse CD47 biAb arm determines the safety, pharmacokinetic properties, and in vivo efficacy in the presence of the CD47 antigen sink." (PMID 31544856, 2018). "In recent years, the therapeutic (re)activation of innate anticancer immunity has gained prominence, with therapeutic blocking of the interaction of Signal Regulatory Protein (SIRP)-α with its ligand CD47 yielding complete responses in refractory and relapsed B cell lymphoma patients." (PMID 38116002, 2023). "Thus, CD47 seems to be a promising therapeutic target only in specific forms of B-cell lymphoma, such as DLBCL, in which it also correlated with poor prognosis, as detailed in our previous work." (PMID 35625912, 2022). "Therefore, DSP107 enhanced macrophage-mediated phagocytosis of B cell lines and primary B cell lymphoma blasts by blocking of CD47-SIRPα interaction." (PMID 35287686, 2022). "The effect of RTX-IgG2 was further validated on Raji B-cell lymphoma cells, which express lower levels of CD20, CD47, and CD59 compared to Granta-519 cells." (PMID 39712032, 2024).
B-cell lymphoma (continued). "Studies have shown that combination therapy with the anti-CD47 mAb TJC4 and Venetoclax significantly enhances synergistic antitumor properties in B-cell lymphoma." (PMID 39060763, 2024). "In this study, utilizing the CD20+CD47high Granta-519 B-cell lymphoma cell line, we found that CD20-mediated apoptosis induced by RTX-IgG2 resulted in a reduction of CD47 expression on the Granta-519 cells." (PMID 39712032, 2024). "In conclusion, our in vitro studies show that RTX-IgG2, in combination with tumor-targeting mAbs, enhances ADCP of CD20+ B-cell lymphoma cells via CD20-mediated apoptosis and CD47 reduction." (PMID 39712032, 2024). "We previously showed that an antibody to SIRPα that blocks its interaction with CD47 markedly enhanced the inhibitory effect of rituximab, an antibody to human (h) CD20, on the growth of human B cell lymphoma in immunodeficient mice." (PMID 38162643, 2023). "A treatment combining anti-CD47 mAb with TTI-621, a SIRPα-Fc fusion protein used to prevent SIRPα:CD47 interaction, was reported to promote the phagocytosis of tumor cells in a B-cell lymphoma mouse model." (PMID 34638388, 2021). "Summary of percentage increase in phagocytosis of CD20+ B-cell lymphoma cells (Granta-519) induced by tumor-specific mAb (anti-CD20 RTX, anti-CD59, or anti-PD-L1) in combination with RTX-IgG2 or anti-CD47 mAb (where applicable) in comparison with single use of tumor-specific mAb." (PMID 39712032, 2024). "In addition, bsAB targeting CD47 and the B-lymphocyte antigens CD20 (IMM0306) or CD19 (TG-1801) also entered clinical testing for patients with B-cell lymphoma or chronic lymphocytic leukemia (CLL), (NCT04806035, NCT03804996) and B-cell NHL (NCT04746131)." (PMID 36900399, 2023). "This is consistent with the emergent clinical success of combining a non-opsonizing anti-CD47 antibody with rituximab in treating CD20+ B cell lymphomas." (PMID 33133093, 2020). "Anti-CD47 antibody in combination with TTI-621, a SIRPα-Fc fusion protein that could block the binding between SIRPα and CD47, promotes phagocytosis of tumor cells in s B-cell lymphoma mouse model." (PMID 33251232, 2020).
cervical cancer (22 papers, 2017 to 2025). A primary or metastatic malignant neoplasm involving the cervix. "This study explored the association between CD24/CD47 expression and macrophage infiltration and clinical outcomes in cervical cancer." (PMID 41354057, 2025). "Our results demonstrated an association between CD47 and cervical cancer as evidenced by the reduced number of macrophages and T cells." (PMID 36894874, 2023). "Cell growth was limited most when aE7 was combined with anti-CD47, which correlates with the strong expression of CD47 in the cervical cancer cell line." (PMID 40006746, 2025). "The expression of CD24 and CD47 was detected by immunohistochemistry in tissue microarrays composed of 130 clinical cervical cancer specimens from Fudan University Shanghai Cancer Center (FUSCC)." (PMID 41354057, 2025). "To investigate the prognostic potential of CD24 and CD47, we performed survival analysis for 264 cervical cancer cases whose survival data and sequencing results were obtained from OncoLnc." (PMID 41354057, 2025). "In this study, we integrated CD24 and CD47 into the analysis of cervical cancer from TCGA and Fudan University Shanghai Cancer Center (FUSCC)." (PMID 41354057, 2025). "Our results provide evidence for the therapeutic potential of CD24 and CD47 blockade, with particular promise for the treatment of cervical cancer." (PMID 41354057, 2025). "From this perspective, combining M1‐polarized macrophage infiltration and CD24/CD47 expression is more effective than CD24/CD47 alone in classifying cervical cancer patients." (PMID 41354057, 2025). "Demographic and histopathologic characteristics of cervical cancer patients with different CD24 or CD47 expression levels." (PMID 41354057, 2025). "The current study was performed to examine the therapeutic potential of CD24 and CD47 blockade in cervical cancer." (PMID 41354057, 2025). "The study provides potential prognostic markers and increases the feasibility of CD24 and CD47 blockade in cervical cancer treatment." (PMID 41354057, 2025). "IL-1RAP also plays an important role in promoting immune escape ability in cervical cancer by expressing CD47 on the surface of tumor cells." (PMID 39461030, 2024). "First, it was observed that IL-1RAP plays an important role during the promotion phase in cervical cancer to acquire immune escape capacity by expressing CD47 (the “don’t eat me” signal) on the surface of tumor cells." (PMID 36499246, 2022). "In response to VES, the protein expression of CD47 on cell membranes and the mRNA level of CD47 in different human cervical cancer cells significantly decreased." (PMID 34093795, 2021). "Collectively, these data provide strong evidence that VES-induced antitumour activity on human cervical cancer cells is coupled to the CD47-SIRPα pathway." (PMID 34093795, 2021). "Collectively, these findings indicate that LSD1 inhibition enhances the therapeutic efficacy of PD-L1/CD47 blockade by reducing CD47 and PD-L1 expression in cervical cancer." (PMID 33731702, 2021). "Meanwhile, the expression of LSD1 in cervical cancer tissues showed a highly positive correlation with CD47/PD-L1." (PMID 33731702, 2021). "Thereafter, the regulation of CD47/PD-L1 protein expression by miR-34a was confirmed by transfecting miR-34a mimics or inhibitors into cervical cancer cells." (PMID 33731702, 2021). "And we are pleased to report our important finding that, through participation in cell-molecular pathways, VES does indeed have the capacity to decrease CD47 expression of human cervical cancer cells in vitro and in vivo." (PMID 34093795, 2021). "In our study, we validated the increase in expression of LSD1 during the progression of cervical cancer and confirmed the enhanced therapeutic effect against cervical cancer when combining CD47/PD-L1 blockade therapy with an LSD1 inhibitor." (PMID 33731702, 2021).
cervical cancer (continued). "In conclusion, our study revealed that LSD1 contributes to cervical cancer immune escape through regulation of CD47/PD-L1 protein expression." (PMID 33731702, 2021). "In the present study, we have demonstrated that CD47 expression in the different human cervical cancer cells in vitro and in the HeLa xenografts of nude mice can be transcriptionally and translationally inhibited in response to VES." (PMID 34093795, 2021). "The humanized CD47-CAR-T cells also specifically killed ovarian, pancreatic, and cervical cancer cell lines and produced IL-2 that correlated with expression of CD47." (PMID 29065481, 2017). "Studies in cervical cancer demonstrate that LSD1 knockdown reduces CD47 and PD-L1 protein expression, with ChIP-Seq analyses revealing elevated H3K4me2 levels at the CD47 and PD-L1 promoter regions following LSD1 inhibition, indicating direct epigenetic regulation." (PMID 41029427, 2025). "Moreover, 12 out of 13 indications had >45% of cases with gain of copy number for CD47, with Cervix cancer having the highest percentage (95%)." (PMID 39627379, 2024). "Moreover, humanized CD47-CAR-T cells specifically killed ovarian, pancreatic, and cervical cancer cell lines, and produced CD47-related IL-2." (PMID 38832992, 2024). "These genes were uploaded to the GEPIA database, which showed that in cervical cancer and paracancerous tissues, the expression levels of seven genes, CD47, FKBP4, IRF-1, LDHA, PDIA3, TFRC, and SLC16A1, were significantly higher in cancer tissues (p < 0.05) than in healthy tissues." (PMID 36894874, 2023). "One can speculate that in the early phase of cervical cancer development, tumor cell populations escape predominantly innate immunity-mediated surveillance through the up-regulation of CD47." (PMID 36611344, 2022). "Therefore, this study revealed the essential role of IL-1RAP in the development of cervical cancers by promoting the expression of the immune escape signal CD47." (PMID 36499246, 2022). "Here, we hypothesised that VES mediates antitumour activity on human cervical cancer cells via the CD47-SIRPɑ pathway in vivo and in vitro." (PMID 34093795, 2021). "Therefore, we decided to examine the expression of CD47 specifically on the surface of cervical cancer cells." (PMID 34093795, 2021). "Moreover, H3K4me2 levels in the CD47/CD274 promoters of SiHa and C33A cells further increased after LSD1 knockdown, suggesting a direct regulatory effect of LSD1-mediated H3K4 demethylation on CD47 and PD-L1 expression in cervical cancer." (PMID 33731702, 2021). "In addition, it was apparent that cervical cancer tissues with high LSD1 expression also had high CD47/PD-L1 expression." (PMID 33731702, 2021). "CD47 and calreticulin levels were analysed using qRT-PCR and flow cytometry to examine whether phagocytosis of the human cervical cancer cells by THP-1 macrophages is mediated by phagocytic molecules." (PMID 34093795, 2021). "In contrast to CD24, which exhibits prognostic implications for cervical cancer irrespective of its association with CD11c, the prognostic value of CD47 is contingent on CD11c, particularly the abundance of infiltrating macrophages within the cervical cancer microenvironment." (PMID 41354057, 2025). "Moreover, inhibition of LSD1 in combination with anti-mouse CD47/PD-L1 mAb could significantly suppress the growth of an allograft model by enhancing the immunogenicity of cervical cancer in vivo." (PMID 33731702, 2021). "Therefore, it may be concluded that the CD47/SIRPα axis plays a very important functional role in the VES-induced anti-tumour activity on human cervical cancer cells." (PMID 34093795, 2021). "This study is the first report investigating dual CD47 and CD24 expressions and comparing their correlation with clinicopathologic and prognostic characteristics in cervical cancer." (PMID 41354057, 2025).